IL1A (interleukin 1 alpha)
Diseases named in the same sentence as IL1A in open-access papers (continued):
Sharing a sentence is not in itself a finding about the gene and the disease.
infection (continued). "The infection of rat coronavirus (RCoV) to the AT1 cells will induce more expression of IL-1α and IL-1β, which will further send more signals through the IL-1 receptor (IL-1R) of the cells not infected in order to induce more CXC chemokine release." (PMID 34367545, 2021). "IL-1α, IL-1β, IL-4, and IL-6 showed infection-specific relative responses, with higher levels in septic TKR than both aseptic TKR and primary TKA (p < 0.05)." (PMID 32708756, 2020). "Infection with RV1b for 48 h produced similar responses, with increased IL-1α and IL-1β following infection significantly associated with necrotic events only in CF AEC, but with apoptotic events in non-CF and CF AEC." (PMID 32328066, 2020). "Using this method, we found that cells isolated from mouse brain can indeed release IL-1α in an infection-dependent manner." (PMID 32703941, 2020). "As expected, elevated concentrations of proinflammatory cytokines were observed during the acute phase of infection in the severe group, including IL-1α, IL-6, IL-8, IL-16, and TNF-α." (PMID 32990499, 2020). "We found a decreased expression of GRO1, CXCL2, CXCL3, and IL1A; these are all important genes for innate immunity during pathogen infection." (PMID 33374309, 2020). "This connection between the coagulation and immune systems allows rapid IL-1α activation and immune cell recruitment that can safeguard against potential infection after breach of the epidermal barrier." (PMID 33391283, 2020). "However, the IL-1α content in the supernatant of Axl−/− macrophages immediately increased after infection, which was maintained at higher levels than that of the control macrophages at all tested time points, suggesting that Axl deficiency promotes the release of IL-1α." (PMID 32611752, 2020). "Pro-inflammatory cytokines like IL-1α, IL-1β, IL-6, and IL-8 have been noted for their roles in early infection response, producing a warning signal of pathogen invasion, and this response was present in septic TKR tissues." (PMID 32867801, 2020). "Using an in situ infection model, we showed that dead macrophages were the primary source of observed increased serum IL-1α levels." (PMID 32611752, 2020). "IL-1β and IL-1α increase acute-phase signaling, homing of immune cells to the site of primary infection and epithelial cell activation, both inducing the production of many other cytokines." (PMID 32397174, 2020). "We found that IL-1α was significantly higher in liver lysates and the serum of cachectic mice at 9 weeks post-infection relative to uninfected controls." (PMID 32973293, 2020). "Infection induced IL-1α and IL-1β production in both phenotypes (p < 0.05) but only correlated with necrosis (IL-1α: r = 0.80; IL-1β: r = 0.77; p < 0.0001) in CF AEC." (PMID 32328066, 2020). "IL-1α protein is present in the brain prior to infection where it is found in microglia as defined by ZsGreen+ or CD11b+CD45int." (PMID 32703941, 2020). "At six weeks post-infection, IL-1α KO mice displayed an increase in parasite burden compared to WT as measured by qPCR analysis of parasite DNA from brain homogenate." (PMID 32703941, 2020). "The keratinocytes secreted an increasing amount of the pro-inflammatory cytokines IL-6 and IL-1α 24 h and 48 h after infection with S. aureus." (PMID 33302597, 2020). "The increased secretion of the proinflammatory cytokines IL-6 and IL-1α as host defense after infection with S. aureus was also observed in 2D and 3D cell models." (PMID 33302597, 2020). "Quantitative analyses of protein secretion (a) and of gene expression (b) for the pro-inflammatory cytokine IL-1α were performed 24 h, 48 h and 72 h after infection." (PMID 32024909, 2020). "Seven cytokines showed infection-dependent increases in localized tissues: IL-1α, IL-1β, IL-6, IL-8, MCP-1, MIP-1α, and MIP-1β (p < 0.05)." (PMID 32867801, 2020).
infection (continued). "Seven cytokines showed an increase in concentration that was dependent on the presence of localized infection: IL-1α, IL-1β, IL-6, IL-8, MCP-1, MIP-1α, and MIP-1β (p < 0.05)." (PMID 32867801, 2020). "Infection of the HaCaT keratinocytes with S. aureus resulted in a considerable IL-1α release after 24 h and 48 h incubation." (PMID 33302597, 2020). "To examine IL-1α release during infection, we first established an assay to measure IL-1α release from isolated brain cells ex vivo." (PMID 32703941, 2020). "CXCL8 is a chemokine that recruits neutrophils to the site of infection, whereas IL-1α was shown to be induced in the skin by commensals where it substantially contributes to skin immunity." (PMID 31227691, 2019). "Epidermal keratinocytes provide barrier function that stops infection, and constitutively express IL-1α." (PMID 30926232, 2019). "We found that the expression of eight genes, including Il18, Il36b, Il17rc, Tnfsf10, Tnfsf11, Tnfsf14, Tnfsf15, and Il1a, were closely correlated with the severity of HAdV-55 infection." (PMID 30787914, 2019). "Data presented here indicate that Cpn stimulated transcription of the proinflammatory cytokine interleukin 1α (IL1α), suggesting that infection of astrocytes by Cpn promoted an inflammatory response." (PMID 30786875, 2019). "In the CNS of Ifnar1−/− mice, IFN-α1, IFN-β, TNF, IL-1α, IL-1β, and IL-6 mRNA levels were increased at day 4 post infection when compared with sham-injected controls." (PMID 31511023, 2019). "In agreement with previous studies, we observed induction of Groα, IL-1α, IL-8, and IL-6 following infection of HeLa cells with serovar L2." (PMID 32039039, 2019). "The effect of Celecoxib treatment on these pathways was evaluated and Celecoxib treatment reduced the upregulation of several critical cytokines including IL-1α and TNFα following infection." (PMID 31842327, 2019). "Although IL-1β was clearly associated with immunopathology in VVC, our study showed that additional inflammasome-dependent cytokines, such IL-1α and IL-18, were produced during infection." (PMID 31681274, 2019). "Systemic levels of both IL-1α and IL-1β were measured in plasma, liver and spleen following infection with the classical European ST1 strain P1/7 and the highly virulent ST7 strain SC84." (PMID 31262357, 2019). "IL-1α coordinates nitric oxide and IL-6 production by macrophages upon infection, but it also acts directly on CD4+IL-17+ T lymphocytes by reprograming their transcriptional profile and potentiating IL-17 production." (PMID 31425553, 2019). "The strain employed in this study (PAO1) lacks the exoU gene, which would account for the relatively low levels of IL-1α detected in the infection assays, particularly in comparison with IL-1β." (PMID 30455194, 2019). "Infection of mice with S. aureus-induced an early inflammatory cytokine response with high levels of IL-1α, IL-1β, IFN-β, TNF-α, IL-6, IL-12p70, IL-27, and IFN-γ in the spleen detected for up to 12 h pi compared to PBS-treated mice." (PMID 31134074, 2019). "In vivo, pulmonary levels of IL-1α increased in the first 7 days of infection but declined to baseline levels at 15 dpi." (PMID 31425553, 2019). "Proinflammatory IL-1 (IL-1α and IL-β), IL-6, and IL-8 are cytokines released from macrophages in response to infection, including that with HIV and M. tuberculosis." (PMID 31341073, 2019). "Ultimately, IL-1α expression often corresponds with neutrophil influx, which is likely involved in controlling infections with a range of B. pseudomallei strains." (PMID 30500862, 2018). "IL-1α release has also been related to neutrophil recruitment and infection control in response to other bacteria such as L. pneumophila." (PMID 30589883, 2018). "Of these genes, only the upregulation of Hspa1a and Il1a was maintained 24 h after infection, and the expression of the heat shock protein 1 (Hspd1) gene was upregulated." (PMID 30555476, 2018).
infection (continued). "Results from these analyses indicated that sagA complemented GAS induces a 2-fold or greater increase in I-309, IL-1α, IL-1β, IL-2, IL-15, MCP-3, MIG, and MIP-1δ compared to the SLS-deficient mutant infection." (PMID 30018884, 2018). "4(b)) and 2(h) post infection displayed significantly increased levels of IL-1α, IL-1β, IL-6, and IL-8 when compared with the uninfected, time-matched control." (PMID 30101649, 2018). "We determine that infected murine microglia produce several pro-inflammatory cytokines as the result of direct infection, including IFNγ, IL-1α, IL-1β, IL-6, and IL-12." (PMID 30400156, 2018). "Activation of TLR4, IL15R, IL1R1, and IL1A is important for antimicrobial activity, a key function for infection control." (PMID 29593724, 2018). "We observed a trend towards increased levels of TNFα, IL-6, IL-1β, and IL-1α in the lung tissue of p110δE1020K-GL mice at 24 h post-infection." (PMID 30093657, 2018). "Recently others reported that pyroptosis leads to secretion of molecules such as IL-1β, IL-1α and eicosanoids which recruit neutrophils to the site of infection promoting phagocytosis of infected cells and contributing to restricting infection." (PMID 30589883, 2018). "We infected BMDMs from C57BL/6, Casp11-/-, Casp1-/-Casp11Tg, Nlrp3-/- and Casp1/11-/- with B. abortus and after 17 hours of infection, we collected supernatant and measured IL-1α release." (PMID 30589883, 2018). "Our analysis indicates that direct TC-83 infection of microglia results in production of numerous pro-inflammatory cytokines, including IFNγ, IL-1α, IL-1β, and IL12p70." (PMID 30400156, 2018). "The ability of cytokines (TNFα in the case of GC, IL-1α for Ct) to exacerbate immune-driven pathology is common to both infections, as is potentially the role of matrix metalloproteinases (MMPs) in tissue disruption." (PMID 30524442, 2018). "Seven to 28 days after infection, significant amounts of IL-1α, IL-1β, MIG, and VEGF were expressed in spleens from BALB/c mice." (PMID 30500862, 2018). "The levels of IL-1α, IL-1β, IL-6, and IL-18 were unchanged or increased in Ccr2-/- mice during infection, likely reflecting increased cytokine production by other immune cell types in response to the substantial increase in bacterial load." (PMID 28384349, 2017). "Among those tested the pro-inflammatory mediators IL1α, IL1β, IFNγ and IL-6 and numerous chemokines were substantially elevated in male lungs as early as 21 days post infection." (PMID 28887521, 2017). "The analysis of the levels of proinflammatory cytokines in geldanamycin-treated mice revealed a significant reduction in TNF-α, IL-6, and IL-1α levels on days 2, 4, or 7 after infection compared with the vehicle-treated and oseltamivir-treated mice." (PMID 28664154, 2017). "We determined the effect of the functional inhibition of IL-1α and/or IL-1β on the resistance of mice to disseminating infections, by blocking IL-1 isoforms with neutralizing antibodies." (PMID 28358036, 2017). "In contrast, most (6/8) male mice treated with the combination of anti-IL-1α plus anti-IL-1β antibodies (anti-IL-1α/β) developed orofacial abscesses beginning 5–7 days after infection, pathognomonic for disseminating dentoalveolar infections." (PMID 28358036, 2017). "And in the present study, MARCO-expressing AMs and MPI cells also exhibit a robust IL-1α response upon infection with Ads." (PMID 28765216, 2017). "With the exception of IL-1α, which was increased following infection, cytokine expression was decreased in the fetus post-infection by at least 60%." (PMID 29176767, 2017). "Type I IFNs (IFN-α and IFN-β) are potent antiviral signal molecules, although they inhibit antibacterial signaling pathways by suppressing inflammatory components of Th1-type immunity, such as IL-1α, IL-1β and type II interferon, and promote infection by Mtb." (PMID 27409673, 2016).
infection (continued). "Pulmonary levels of IFNγ, IL-1α, IL-1β and CXCL1/KC were highly increased in TNFα-deficient mice one month after infection, when severe pathology develops, with a reduction of IL-12/23p40 and p19, in line with transcriptome data." (PMID 27853279, 2016). "The availability of preformed IL-1α from keratinocytes, which are the first cells to be exposed to C. albicans during infection, is critical for the initiation of the response." (PMID 27632536, 2016). "Quantitative reverse transcription-PCR data showed that 30 min post PAO1 infection, transcriptions of all tested NF-κB-dependent genes, including IL-1α, IL-1β, IL-6, IFN-γ, MCP-2, MIP1α, TNF-α and TLR2, were significantly increased in Lyn-silenced MH-S cells." (PMID 29263906, 2016). "Similar to the dsRNA-challenged polarized EMTU model, HRV16 infection induced IL-1α release from HBEC ALIs which was higher in the apical compared to the basolateral compartment." (PMID 27583193, 2016). "Young mice had increased levels of inflammatory cytokines G-CSF, IL-6, and IL-1α, which peaked at 6 dpi and then returned to baseline by day 12 as the infection was resolving." (PMID 27177221, 2016). "We measured many cytokines and chemokines that play important roles in shaping the early immune response to infection, yet ex vivo production of IL-1α was the only one that was significantly affected by dietary S. frutescens consumption." (PMID 27575007, 2016). "There was also a significant reduction in the levels of the interleukins IL1-α and IL-1β released when fkh2(6A) was used in the infection model." (PMID 25617770, 2015). "IL-1α is secreted by activated macrophages and neutrophils, as well as epithelial cells, stimulating inflammation early after onset of infection." (PMID 26473163, 2015). "It has also been demonstrated that IL-1α plays a critical role during murine L. pneumophila infection, initiating neutrophil recruitment and the inflammatory response early after infection." (PMID 25629406, 2015). "IL-8 concentrations increased significantly throughout the course of infection (p<0.001), with IL-1α and IL-6 demonstrating a trend in increasing concentration over time (p=0.936, p=0.191, respectively)." (PMID 26473163, 2015). "Treatment with anti-diabetic drugs metformin and glibenclamide also reduced IL-1α and IL-1β secretion in infection and cytokine-primed adipose tissue." (PMID 25849717, 2015). "Lung-resident myeloid cells represent a potential source of IL-1α and IL-1β at the earliest time point post-infection." (PMID 25621893, 2015). "Levels of cytokines that showed large differences between EP and S. mitis (IL-1α, IL-6, KC, M-CSF and TNFα) were assayed in chamber fluid collected at 24 and 168 h after infection with the individual species." (PMID 26171605, 2015). "It is of interest, therefore that expression of IL-1α is relatively low at early times, increasing more than 6 fold in EP infected chambers at later times of infection, at the same time as IL-6 expression is being reduced." (PMID 26171605, 2015). "The cytokine interleukin-1 (IL-1) has two main pro-inflammatory forms, IL-1α and IL-1β, which are central to host responses to infection and to damaging sterile inflammation." (PMID 24790078, 2014). "The kinetics of pro-IL-1α and pro-IL-1β production in infected cells indicated that there was enhanced accumulation of these proteins between 4–6 hrs post-infection." (PMID 25058342, 2014). "We have shown that pro-IL-1α and pro-IL-1β accumulate in cells that harbor L. pneumophila between 4–6 hrs post infection, despite a significant block in protein translation." (PMID 25058342, 2014). "Consistent with our intracellular cytokine staining and Western blot data, the highest levels of IL-1α and IL-1b synthesis were detected between 5–6 hrs post-infection." (PMID 25058342, 2014).
infection (continued). "Similar to the mRNA expression, protein levels of IL-1β, TNF, IL-6, IFNγ, and IL-1α were also significantly elevated in the brains of db/db mice when compared to WT mice at day 8 after infection as measured by the multiplex immunoassay (P <0.05)." (PMID 24750819, 2014). "Time course analysis of intracellular IL-1α levels using flow cytometry confirmed that the highest level of IL-1α accumulation occurred between 2–6 hrs post infection in the GFP+ population." (PMID 25058342, 2014). "Infection of bone-marrow macrophages with virulent (Dot+) L. pneumophila induced Il1α, Il1β and Tnfα transcripts by 6 hrs post infection." (PMID 25058342, 2014). "Of course during infection and tissue damage, host cells are exposed to both PAMPs and DAMPs, and it was notable that the quantitative response to 10 ng/ml IL-1α and 0.1 μg/ml LPS were similar." (PMID 25395028, 2014). "As expected, we found that dystocia and infection are rarely independent in vivo, although the localized accumulation of IL-1α in vaginal mucus of diseased animals was notable." (PMID 25395028, 2014). "Having shown that infection of NHBE cells with HRV triggers the release of IL-1α, IL-1β and IL-18, we investigated the extent of the contribution of these cytokines to the release of other mediators by autocrine mechanisms." (PMID 23723976, 2013). "Significant induction (p≤0.0012) in IL-1α production was also detected extracellularly but only at 24h post-infection at the highest doses (100 and 1000 MOI)." (PMID 24349452, 2013). "In severe S. aureus bacteraemia in mice, TNF-α, IL-1α, and KC are biomarkers predicting fatal outcome of infection." (PMID 23520553, 2013). "This study provides evidence that in severe S. aureus bacteremia in mice, TNF-α, IL-1α, and KC each can be useful as biomarkers predicting fatal outcome of infection." (PMID 23520553, 2013). "IL33 expression showed a similarly modest change in expression as IL1A, with levels of mRNA increasing by ∼fourfold at 2 h post-infection." (PMID 24137162, 2013). "To determine the relative contributions of IL-1α and IL-1β to neutrophil recruitment and bacterial clearance during L. pneumophila infection, we utilized neutralizing antibodies to selectively block either IL-1α or IL-1β prior to infection." (PMID 23762026, 2013). "Unprimed BMDMs secrete robust levels of IL-1α and IL-1β by 20 hours post-infection with wild-type L. pneumophila (WT Lp)." (PMID 23762026, 2013). "In vivo, IL-1R1 deficiency was shown to result in enhanced Th2-type immune responses following infection with the protozoan parasite Leishmania major and IL-1α was reported to promote Th1-biased immune resistance to Leishmania major." (PMID 23935505, 2013). "Our data indicated that although IL-1R1 pathway is essential for controlling acute infection by virulent M. tuberculosis, presence of either IL-1α or IL-1β allowed to survive acute M. tuberculosis infection." (PMID 25400917, 2013). "IL1A expression was slightly enhanced by short-term infection, although only increased over uninfected cells by ∼fourfold at 120 min." (PMID 24137162, 2013). "Among other genes found to display high, and significant expressional levels during infection were IL-1α, IL-32, growth differentiation factor 15 (GDF15) and, chemokine (C-C motif) ligand 22 (CCL22)." (PMID 23646188, 2013). "Lung IFNγ levels were highly elevated in mice deficient for both IL-1α and IL-1β or for IL-1R1 at 5 weeks after M. tuberculosis infection, reminiscent of TNF deficient mice at 4 weeks, when they succumb to infection." (PMID 25400917, 2013). "IL-1α is also mainly produced by activated macrophages early after onset of infection, and plays one of the central roles in the regulation of immune responses." (PMID 23520553, 2013). "Interleukin-1 (IL-1) family members, such as IL-1α, IL-1β, IL-1ra, and IL-18, are produced by various cells, such as lymphocytes, in response to inflammation produced by infection and microbial endotoxins." (PMID 23533315, 2013).